TRIM27 (tripartite motif containing 27)
Diseases named in the same sentence as TRIM27 in open-access papers (continued):
Sharing a sentence is not in itself a finding about the gene and the disease.
infection (4 papers, 2016 to 2024). The state of being infected such as from the introduction of a foreign agent such as serum, vaccine, antigenic substance or organism. "It has been indicated that miR-324-3p can regulate the expression of TRIM27 to reduce viral replication during infection, and TRIM27 is a negative regulator of IFN-α/β to induce antiviral immune response." (PMID 38178220, 2024). "The confocal images also demonstrated that knockdown of linc-AhRA attenuated the HSV-1-induced co-localization of TBK1 with TRIM27 at the late stage of infection." (PMID 34646390, 2021). "We observed a much higher level of cleaved caspase 3 in WT U937 cells than that in TRIM27-KD U937 cells or TRIM27 (ΔRING)-expressing U937 cells, especially at 48 h post-infection." (PMID 27698396, 2016). "Consistently, flow cytometry analysis data showed that the number of the early and late apoptosis cells significantly reduced in TRIM27-KD U937 cells and TRIM27 (ΔRING)-expressing U937 cells compared with that in WT U937 cells at 24 h post- infection." (PMID 27698396, 2016). "We found that knockdown of TRIM27 efficiently suppressed the production of IL-1β and IL8 in BCG-infected macrophages since 2 h post-infection, and the complementation with TRIM27 ΔRING exhibited the same suppression effects." (PMID 27698396, 2016). "After infection by mycobacteria, the protein levels of TRIM27 in macrophages significantly increased since 2 h post-infection and reached its highest level at 8 h post-infection, followed by a sharp decrease in later time points." (PMID 27698396, 2016). "In addition, infection of BCG or M. smegmatis induced expression of TRIM27 in U937 cells at 2 h post-infection, followed by decline at later time points." (PMID 27698396, 2016). "In contrast, TRIM27 interacted with linc-AhRA in an HSV-1-infection-independent manner, and HSV-1 infection strengthened the linc-AhRA-TRIM27 interaction." (PMID 34646390, 2021). "Knock-down of TRIM27 significantly promoted the intercellular survival of BCG and M. smegmatis from 8 h post-infection of U937 cells." (PMID 27698396, 2016). "Furthermore, we also found that COX-5B was significantly up-regulated, while TRIM25, TRIM21, TRIM27 and TRIM26 were significantly down-regulated in the PAMs with a PRRSV-ADE infection in this study." (PMID 36680075, 2022). "Additionally, confocal microscopy imaging revealed a co-localization of TRIM27 and TBK1 in the cytoplasm and nuclear export of TRIM27 in the late stage of infection." (PMID 34646390, 2021). "Macrophage-like U937 cells (differentiated from U937 human monocytic cells) were transfected with negative control small interfering RNA (NC siRNA) or TRIM27-specific siRNA, followed by infection with mycobacteria." (PMID 27698396, 2016). "Immunoblot analysis data showed that knockdown of TRIM27 in U937 cells led to the suppression of JNK and p38 phosphorylation but increased IκBα phosphorylation compared with wild-type (WT) U937 cells, especially at 48 h post-infection." (PMID 27698396, 2016).
adenocarcinoma (1 paper, 2020). A common cancer characterized by the presence of malignant glandular cells. "Other co-regulated genes of potential interest include TRIM27 (FDR-adjusted p = 0.025), as well as NT5DC1 (FDR-adjusted p = 0.003) and ARL6IP1 (FDR-adjusted p = 0.047), which were upregulated in the A549 adenocarcinoma alveolar basal epithelial cell line after exposure to IFN-α and IFN-γ for 6 h." (PMID 32413319, 2020).
musculoskeletal diseases (1 paper, 2025). "Furthermore, we propose that pharmacological approaches targeting TRIM27 may also contribute to the development of treatments for musculoskeletal diseases." (PMID 40251491, 2025).
TRIM27 also shares sentences with these, for which no sentence is quoted: graft versus host disease (2 papers); schizophrenia (2); agranulocytosis (1); bone metabolism disorders (1); cleft palate (1); colon adenoma (1); depression (1); epilepsy (1); glioma (1); granulocytopenia (1); Hematuria (1); ischemic stroke (1); lentivirus infection (1); leukemia (1); nephrotic syndrome (1); Obesity (1); Parkinson disease (1); sarcopenia (1); seminoma (1); skeletal diseases (1).